MIR6503 (microRNA 6503)
Synonyms: hsa-mir-6503
Gene: MicroRNA gene on chromosome 11 (60,209,071 to 60,209,156, reverse strand). Ensembl gene ENSG00000275344.
Homologues: Orthologues: chimpanzee MIR6503 (100% identical).